LRPAP1 (LDL receptor related protein associated protein 1)
Diseases named in the same sentence as LRPAP1 in open-access papers:
LRPAP1 is named in the same sentence as 68 diseases in open-access papers, as found by Europe PMC text mining. Sharing a sentence is not in itself a finding about the gene and the disease. The quoted sentences say what the papers report.
Alzheimer disease (9 papers, 2010 to 2023). A progressive, neurodegenerative disease characterized by loss of function and death of nerve cells in several areas of the brain leading to loss of cognitive function such as memory and language. "Consistently, LRP-1 is involved in the export of Aβ from the brain, while LRPAP1 gene polymorphisms are associated with late-onset Alzheimer’s disease." (PMID 36012423, 2022). "Genetic variants of LRPAP1 have been linked to dementia, late-onset Alzheimer’s disease and Parkinson’s disease, and such variants may be unable to bind LRP1 correctly." (PMID 38035103, 2023). "Microglial phagocytosis of synapses may contribute to synapse loss in neurogenerative diseases, such as Alzheimer’s disease, and, if so, we might expect extracellular LRPAP1 to be protective." (PMID 38035103, 2023). "Also found near rs1078701 is LRPAP1 which produces a glycoprotein that has been linked with gallstone disease caused by an excess of cholesterol and with cholesterol-related brain disorders such as dementia and Alzheimer's disease." (PMID 22577559, 2012). "LRPAP1 is also present in the cerebrospinal fluid, and mildly decreases with minor cognitive impairment and mildly increases in Alzheimer’s disease." (PMID 38035103, 2023). "LRP1 that binds to LRPAP1 has been shown to be involved in the clearance of the β-amyloid protein, which accumulates in the brain of patients with Alzheimer's disease." (PMID 21603600, 2011). "Thus, extracellular LRPAP1 can potentially block TAU spreading in Alzheimer’s disease and other TAU pathologies." (PMID 38035103, 2023). "Having found that LRPAP1 inhibits microglial phagocytosis of synaptosomes and cells, we next tested whether LRPAP1 affected Aβ uptake by BV-2 or CHME3 microglia, an activity relevant to Alzheimer’s disease." (PMID 38035103, 2023).
myopia (7 papers, 2017 to 2025). "LRPAP1 interacts with the low density lipoprotein receptor‐related protein, and reports have shown that this gene was associated with myopia and Parkinson's disease." (PMID 28796930, 2017). "We screened for mutations in SLC39A5, LEPREL1 and LRPAP1 in a cohort of 187 high myopia patients with Sanger sequencing." (PMID 28442722, 2017). "Additionally, we found recessive types of non-syndromic high myopia that have a high chance of causing retinal detachment, like those linked to LRPAP1 and LEPREL1." (PMID 40725504, 2025). "TGF-β signaling has also been shown to be involved in myopia, particularly in the remodeling of the sclera extracellular matrix; the loss of function of LRPAP1 may lead to a decrease in LRP1, which in turn activates TGF-β signaling." (PMID 36261846, 2022). "Altogether, our results provide new insights into the mechanisms underlying LRPAP1-related myopia." (PMID 36261846, 2022). "Therefore, we screened mutations in the three HM associated genes, SLC39A5, LEPREL1 and LRPAP1, and discovered additional mutations in a group of 187 unrelated Chinese patients with high myopia." (PMID 28442722, 2017). "SLC39A5, LEPREL1 and LRPAP1 were more likely to associate with Chinese high myopia patients." (PMID 28442722, 2017). "Such extreme myopia in a young child from this region of the world should raise suspicion for mutations in LRPAP1, but the time he was assessed and included in this study was before we had a clear understanding of the features that suggest LRPAP1‐related extreme myopia." (PMID 33951325, 2021). "In the present study, we found that LRPAP1, a gene related to myopia, was elevated in giant pandas, which provided a new clue for the giant pandas’ poor eyesight." (PMID 32292275, 2020). "In order to expand the mutation spectrum of the causative genes in Chinese adult population, we investigated three genes, SLC39A5, LEPREL1 and LRPAP1, in a cohort of 187 independent Chinese patients with high myopia." (PMID 28442722, 2017). "The other was found to have LRPAP1‐related very high myopia (subject #11)." (PMID 33951325, 2021). "However, whether TGF-β was interacted with LRPAP1 in regulation of myopia development remains unknown." (PMID 36261846, 2022). "Therefore, LRPAP1 may affect the formation of myopia by regulating TGF-β signaling." (PMID 28442722, 2017).
mantle cell lymphoma (4 papers, 2020 to 2024). Mantle cell lymphoma is a rare form of malignant non-Hodgkin lymphoma affecting B lymphocytes in the lymph nodes in a region called the ``mantle zone''. "Regarding more aggressive lymphomas, LRPAP1 was found to be a frequent antigen of the BCRs on mantle cell lymphoma (MCL) including the cell lines MAVER1 and Z138." (PMID 36051037, 2022).
lymphoma (3 papers, 2022 to 2024). A malignant (clonal) proliferation of B- lymphocytes or T- lymphocytes which involves the lymph nodes, bone marrow and/or extranodal sites. "Marijt and colleagues identified a human HLA-A2-binding TEIPP derived from the LDL Receptor Related Protein Associated Protein 1 (LRPAP1) signal sequence (LRPAP121-30) common to different type of tumors, including melanoma, lymphoma, colon and renal cell carcinoma." (PMID 35936007, 2022). "Fabs were then tested for specific binding against the common lymphoma BCR antigens SAMD14/neurabin-I, LRPAP1, RpoC and galectin-3 using ELISA9,10,12,21,41." (PMID 38671086, 2024).
melanoma (3 papers, 2019 to 2025). A malignant, usually aggressive tumor composed of atypical, neoplastic melanocytes. "Treatment of melanoma or renal cancer tumor cells with Nucl-TAP led to the activation of lentiviral transduced CD8+ T cells expressing the TCR specific to LRPAP1 peptide as measured by the acquisition of cytotoxic and IFNγ-secreting effector functions." (PMID 31434881, 2019).
glioblastoma (2 papers, 2011 to 2023). The most malignant astrocytic tumor (WHO grade IV). "Importantly, we observed a fusion, LRPAP1-PDGFRA, in a glioblastoma and a germ cell tumor." (PMID 37990009, 2023).
leukemia (2 papers, 2018 to 2021). A malignant (clonal) hematologic disorder, involving hematopoietic stem cells and characterized by the presence of primitive or atypical myeloid or lymphoid cells in the bone marrow and the blood. "It is noted that LRPAP1 is a biologically relevant gene found in leukemia and was associated with different biological processes including cell apoptosis, signaling pathway and cell cycle checkpoint." (PMID 29933410, 2018). "LRP8, an indicator of poorer prognosis was highly expressed in metastatic TNBC cells according to scRNA-seq data, and its ligand LRPAP1 was reported to induce T-cell proliferation in leukemia." (PMID 34611125, 2021).
retinal detachment (2 papers, 2021 to 2025). An eye emergency condition which may lead to blindness if left untreated. "However, there are other rarer causes for pediatric retinal detachment, such as biallelic LRPAP1 mutations, the underlying genotype for subject #11 (discussed further below)." (PMID 33951325, 2021).
virus infection (2 papers, 2023 to 2024). "Taken together, these results suggested a crucial role for the secreted LRPAP1 in facilitating virus infection both in vitro and in vivo." (PMID 37743411, 2023). "Therefore, we used coronavirus 3CLpro as a representative to further explore the effect of multiple proteases on LRPAP1 and viral infection." (PMID 37743411, 2023). "LRPAP1 antibody treatment also significantly protected cells from cytopathic effects (CPE) caused by virus infection, indicating the extracellular LRPAP1 induced by HCoV-OC43 promoted viral infection." (PMID 37743411, 2023). "These indicated that the promoted extracellular LRPAP1 caused by viruses to improve viral infection was a conserved strategy, which applied to non-enveloped viruses and enveloped viruses with RNA or DNA genome." (PMID 37743411, 2023). "Therefore, we concluded that the inhibition of LRPAP1 reduced multiple viral infections that were not limited to RNA viruses (coronavirus, enterovirus, flavivirus), but also applied to DNA viruses (herpes virus and hepadnavirus)." (PMID 37743411, 2023). "As a ligand, the N-terminus of secreted LRPAP1 binds with the extracellular domain of IFNAR1 that triggers the receptor ubiquitination and degradation and promotes virus infection both in vitro, ex vivo in the mouse brain, and in vivo in newborn mice." (PMID 37743411, 2023).
B‐cell lymphoma (1 paper, 2023). "Still, the BAR‐body concept may be a powerful tool as an additional future treatment option for B‐cell lymphomas considering that several B‐cell lymphoma autoantigens have already been identified, including LRPAP1, neurabin‐I/SAMD14, and Ars2." (PMID 36819155, 2023).
depressive disorder (1 paper, 2012). A melancholy feeling of sadness and despair. "Among the cognate genes, six including ALG8, DGKE, GNA12, KLF11, LRPAP1, and MMAB are related to multiple genetic diseases such as depressive disorder and Type-II diabetes." (PMID 22348086, 2012).
Hypertension (1 paper, 2024). The presence of chronic increased pressure in the systemic arterial system. "Furthermore, the combination of hsa-miRNA-5589–5p and LRPAP1 may have diagnostic utility for hypertension." (PMID 38836231, 2024). "While miRNA-mRNA networks have previously been utilized to detect markers for various diseases, including hypertension, the regulatory networks involving LRPAP1, KIAA0513, and ARID3A have been less explored." (PMID 38836231, 2024). "In conclusion, these results indicate that mRNAs KIAA0513, LRPAP1, ARID3A, and hsa-miRNA-5589–5p can be considered as diagnostic biomarkers for patients with hypertension." (PMID 38836231, 2024). "LRPAP1, involved in the suitable localization and folding of LDL receptor-related protein (LRP1), has known associations with hypertension and angiogenesis, a potential avenue for hypertension treatment." (PMID 38836231, 2024). "Among these mRNAs, ARID3A, LRPAP1, and KIAA0513, along with hsa-miRNA-5589–5p, demonstrated associations with hypertension." (PMID 38836231, 2024). "Additionally, public data revealed that CEBPA binding peaks were present upstream of LRPAP1 and ARID3A, strengthening the possibility of CEBPA’s regulatory role in hypertension." (PMID 38836231, 2024). "Notably, this analysis revealed that LRPAP1, ARID3A, and KIAA0513 may have the potential to influence hypertension." (PMID 38836231, 2024).
lung adenocarcinoma (1 paper, 2025). A carcinoma that arises from the lung and is characterized by the presence of malignant glandular epithelial cells. "LRPAP1 is shown as a key player in the micropapillary pattern metastasis of lung adenocarcinoma." (PMID 41226668, 2025).
metastatic tumors (1 paper, 2025). "Likewise, LRPAP1, MSX1, CCND2, and NRP1 displayed strong associations with monocytes, Tregs and NK cells, especially in metastatic tumors." (PMID 40943183, 2025).
multiple sclerosis (1 paper, 2023). A progressive autoimmune disorder affecting the central nervous system resulting in demyelination. "Thus, if LRPAP1 is released during demyelination it might inhibit myelin clearance, which is thought to be important in multiple sclerosis." (PMID 38035103, 2023).
myocardial infarction (1 paper, 2022). Gross necrosis of the myocardium, as a result of interruption of the blood supply to the area, as in coronary thrombosis. "Also, the LRPAP1 gene encodes the LDL receptor-related protein associated with early onset myocardial infarction." (PMID 35614300, 2022).
Senile plaques (1 paper, 2018). Senile plaques are extracellular deposits of amyloid in the gray matter of the brain. "Co-localization of Aβ, APOE and LRPAP1 on senile plaques suggests its involvement in the clearance of APOE/Aβ complex." (PMID 29551980, 2018).
Sepsis (1 paper, 2025). Sepsis is defined as life-threatening organ dysfunction caused by a dysregulated host response to infection. "In this study, we conducted differential gene expression and mendelian randomization (MR) analyses to target three regulated risk sepsis genes (core sepsis genes: LRPAP1, NTSR1, and SEMA4A)." (PMID 40756031, 2025). "We identified 307 highly expressed DEGs and 72 disease-related risk genes, culminating in the identification of three core sepsis genes including SEMA4A, LRPAP1, and NTSR1." (PMID 40756031, 2025). "Given the critical role of alterations in lipid metabolism in sepsis pathophysiology, our study sheds light on the regulatory function of LRPAP1 in lipid metabolism during sepsis." (PMID 40756031, 2025). "Notably, the analysis highlighted LRPAP1, NTSR1, and SEMA4A as up-regulated risk genes in sepsis (core sepsis genes)." (PMID 40756031, 2025). "This study offers a comprehensive analysis of genes contributing to sepsis by combining transcriptomics, MR, single-cell sequencing, and in vitro experiments, with a particular emphasis on SEMA4A, LRPAP1, and NTSR1." (PMID 40756031, 2025). "While the differential expression analysis of the dataset indicated that upregulation of NTSR1, LRPAP1, and SEMA4A in sepsis, our in vitro experiments revealed that only SEMA4A was upregulated in the model group." (PMID 40756031, 2025). "To gain deeper insights into the functions and pathways influenced by three core genes in sepsis, we conducted GO and KEGG enrichments among groups with high and low expression of NTSR1, LRPAP1, and SEMA4A genes." (PMID 40756031, 2025). "The results confirmed significantly higher expression levels of LRPAP1, NTSR1, and SEMA4A in these additional sepsis samples compared to the control group." (PMID 40756031, 2025). "Among three core sepsis genes, only SEMA4A was upregulated in the model group, whereas LRPAP1 and NTSR1 exhibited decreased expressions, contrary to previous results." (PMID 40756031, 2025). "Additionally, correlation studies between core sepsis genes and immune cells unveil potential roles and regulatory effects of NTSR1, LRPAP1, and SEMA4A on immune cells in sepsis." (PMID 40756031, 2025). "This study proposes SEMA4A, LRPAP1, and NTSR1 as promising therapeutic targets for sepsis." (PMID 40756031, 2025).
Stickler syndrome (1 paper, 2021). Stickler syndrome is an inherited vitreoretinopathy characterized by the association of ocular signs with more or less complete forms of Pierre-Robin sequence, bone disorders, and sensorineural deafness (10% of cases). "Biallelic mutations in LRPAP1 can result in a phenotype that may resemble Stickler syndrome." (PMID 33951325, 2021).
tumor (9 papers, 2017 to 2025). "In another study, reactivity with the autoantigen low-density lipoprotein receptor-related protein-associated protein 1 (LRPAP1) was identified in 36% (10/28) of investigated tumor immunoglobulins." (PMID 32481736, 2020). "Several additional genes—including FSTL1, LRPAP1, MSX1, and APP—exhibited distinct immune interaction profiles, suggesting diverse roles in modulating tumor–immune dynamics." (PMID 40943183, 2025). "We found that in both metabolism-related pathways, SLC5A3 + tumor cells exhibit significant communication with CAFs, particularly through the FN1/SDC2, FGF7/FGFR1, NGF/SORT1, and LRPAP1/LRP1 receptor-ligand pairs." (PMID 40652057, 2025). "Similarly, LRPAP1 and KCNJ8 showed negative correlations with CD8+ T cells and positive correlations with macrophages and certain memory B cell subsets, suggesting that these genes may shift immune cell composition in ways that impact tumor immunity." (PMID 40943183, 2025).
cancer (7 papers, 2015 to 2025). A tumor composed of atypical neoplastic, often pleomorphic cells that invade other tissues. "LDL receptor related protein associated protein 1 (LRPAP1) is a gene that involved in the cell proliferation in cancer." (PMID 29933410, 2018). "One of the identified antigens derived from the signal sequence of the LRPAP1 protein and was presented on multiple TAP-deficient cancer types, including renal cell carcinoma, lymphoma, melanoma, and colon carcinoma." (PMID 34142235, 2022). "LRPAP1 expression was similar between cancer cell lines and healthy cells, with moDC having approximately four times higher levels than the cancer lines." (PMID 34142235, 2022). "The high-intensity stained LRPAP121–30-specific T cells responded strongly to TAP-deficient cancer cells, but not to the LRPAP1-positive healthy cells." (PMID 34142235, 2022). "Interestingly, many of the DMGs identified had multiple roles and several were potential cancer biomarkers or were previously shown to be implicated in various types of cancers, including ABLIM1, ADAM12, ARHGEF4, FBLN2, ITGA6, LRPAP1, Ly9, NT5E, PITPNC1, PLCG1, OBSCN, RHOH, SPTBN1, SPOCK2 and SPRY1." (PMID 41159936, 2025).
infection (6 papers, 2013 to 2025). The state of being infected such as from the introduction of a foreign agent such as serum, vaccine, antigenic substance or organism. "Subsequently, the effect of secreted LRPAP1 induced by coronavirus 3CLpro was tested on other viruses’ infection." (PMID 37743411, 2023). "We discovered significantly decreased infections after silencing LRPAP1, including picornavirus, coronavirus, flavivirus, herpesvirus, and hepadnavirus." (PMID 37743411, 2023). "Additionally, LRPAP1 antibody significantly decreased EV71 induced CPEs when it was added into the culture medium 3 h post infection." (PMID 37743411, 2023). "The decreased intracellular HSV-1 DNA level and TCID50 were observed after adding LRPAP1 antibody, while a less obvious CPE was found with the infection of HSV-1." (PMID 37743411, 2023). "Although transcriptomic and proteomic data showed that many viruses (e.g., HCV, LCMV, EBV, KSHV, and SARS-CoV-2) upregulate LRPAP1,20,21 its function in infections has not yet been characterized." (PMID 37743411, 2023).
bacterial infections (1 paper, 2023). "We expect that LRPAP1 inhibitors could be rapidly developed and used for the treatment of multiple viral and bacterial infections." (PMID 37743411, 2023).
LRPAP1 also shares sentences with these, for which no sentence is quoted: atherosclerosis (2 papers); breast carcinoma (2); chronic lymphocytic leukemia (2); cognitive defects (2); dementia (2); glioma (2); neurological diseases (2); amyloid (1); Arthritis (1); aseptic meningitis (1); brain disorder (1); congenital disorder of glycosylation (1); coronary artery disease (1); COVID-19 (1); cystinosis (1); diffuse large B-cell lymphoma (1); diphtheria (1); dyslipidemia (1); encephalitis (1); frontotemporal lobar degeneration (1); genetic diseases (1); germ cell tumor (1); head and neck cancer (1); Hypercholesterolemia (1); lung carcinoma (1); lysosomal storage disorders (1); major depressive disorder (1); mental disorder (1); myeloma (1); neurodegenerative disease (1).
A further 15 diseases each share a sentence with LRPAP1 in 1 paper.